NTN4 (netrin 4)
Description:
May play an important role in neural, kidney and vascular development. Promotes neurite elongation from olfactory bulb explants.
Synonyms: PRO3091
Tractability: Antibody: UniProt places it where antibodies can reach, with high confidence; its Gene Ontology location is reachable by antibodies, with high confidence; UniProt predicts a signal peptide or a membrane-spanning region. PROTAC: ubiquitination databases record sites on it; its protein half-life has been measured.
Gene: Protein-coding gene on chromosome 12 (95,657,807 to 95,791,189, reverse strand). Ensembl gene ENSG00000074527.
Subcellular location: Secreted, extracellular space, extracellular matrix, basement membrane
Pathways (Reactome):
Developmental Biology: Netrin-1 signaling
Extracellular matrix organization: Non-integrin membrane-ECM interactions
Gene Ontology:
Molecular function: protein binding; laminin-1 binding
Biological process: animal organ morphogenesis; axon guidance; basement membrane assembly; cell migration; substrate adhesion-dependent cell spreading; tissue development
Cellular component: laminin complex; plasma membrane; basement membrane
Genetic constraint (gnomAD): Loss-of-function variants: 23 observed, 61.11 expected, observed/expected ratio (o/e) 0.38, 90% interval 0.27 to 0.53. The upper end of that interval is the gene's LOEUF score, 0.53, which puts it in group 2 of 6, group 1 being the genes least tolerant of losing a copy. Missense variants: 588 observed, 731.94 expected, observed/expected ratio (o/e) 0.8, 90% interval 0.75 to 0.86. Synonymous variants: 232 observed, 265.6 expected, observed/expected ratio (o/e) 0.87, 90% interval 0.78 to 0.97.
Homologues: Orthologues: chimpanzee NTN4 (99% identical), macaque NTN4 (98% identical), dog NTN4 (92% identical), pig NTN4 (91% identical), rabbit NTN4 (90% identical), mouse Ntn4 (90% identical), rat Ntn4 (90% identical), guinea pig NTN4 (88% identical), tropical clawed frog NTN4 (71% identical), zebrafish ntn4 (51% identical). Paralogues in human: LAMB1 (37% identical), LAMB2 (36% identical), LAMB4 (35% identical), LAMA5 (29% identical), LAMA2 (29% identical), LAMA1 (29% identical), LAMA3 (29% identical), LAMB3 (28% identical), LAMC1 (28% identical), LAMC3 (27% identical), NTN1 (26% identical), USH2A (25% identical), and 15 more.
Diseases named in the same sentence as NTN4 in open-access papers:
NTN4 is named in the same sentence as 70 diseases in open-access papers, as found by Europe PMC text mining. Sharing a sentence is not in itself a finding about the gene and the disease. The quoted sentences say what the papers report.
breast carcinoma (30 papers, 2010 to 2024). "This is consistent with studies in other diseases, such as breast cancer, where NTN4 expression was positively associated with immune cell infiltration." (PMID 39518922, 2024). "Studies have indicated that NTN4, acting as a susceptibility locus, is capable of inhibiting breast cancer growth and reducing the invasiveness of cancer cells through the regulation of EMT." (PMID 37345154, 2023). "Among four cohorts (GSE6532-GPL570, GSE1379, GSE3494-GPL97, GSE4922-GPL97) including different stages of breast cancer, high NTN4 expression was associated with favorable prognosis." (PMID 35732855, 2022). "Potential molecular function and regulation pathway of NTN4 were preliminarily explored to demonstrate the potential mechanism underlying how NTN4 regulates biological behaviors of breast cancer." (PMID 35732855, 2022). "In this study, association between NTN4 mRNA and breast cancer prognosis was evaluated by using public databases such as Kaplan–Meier plotter and PrognoScan." (PMID 35732855, 2022). "Netrin-4 expression was screened to be a biomarker in estrogen receptor α positive breast carcinomas, which are associated with favorable prognosis as well." (PMID 30923634, 2019). "NTN4 has been implicated as a prognosis marker of certain malignancies such as gastric and breast cancer." (PMID 30160193, 2019). "In addition, associations of NTN4 mRNA levels with clinicopathological characteristics and tumor-infiltrating immune cells were investigated in breast cancer." (PMID 35732855, 2022). "Besides, NTN4 is associated with immune infiltration and survival in breast cancer." (PMID 35732855, 2022). "NTN4/PRO3091 gene encodes a member of the netrin family of proteins (netrin 4), which participates in various biological processes, including tumorogenesis and angiogenesis; in fact, netrin-4 is reduced in breast cancer tissue and is associated with breast cancer cell migration and invasion." (PMID 35295987, 2022). "Therefore, it is conceivable that low NTN4 expression might be a risk factor for a poor prognosis in breast cancer patients." (PMID 35732855, 2022). "In breast cancer, only about 40% of tumors expressed detectable amounts of NTN4 at the protein level, and the expression of NTN4 was associated with better overall survival and disease-free survival." (PMID 38175202, 2024). "It has also been shown that the high expression of NTN4 is beneficial in improving the survival rate of breast cancer patients." (PMID 37345154, 2023). "According to relative NTN4 levels, breast cancer patients were divided into low (n = 541) and high (n = 542) expression groups." (PMID 35732855, 2022). "Our findings shed light on the role of NTN4 in breast cancer and provided potential interaction between NTN4 and the TME." (PMID 35732855, 2022). "The NTN4 mRNA expression was significantly lower in invasive breast carcinoma compared with adjacent tissues, while increasing NTN4 mRNA levels are related to favorable prognosis in breast cancer patients." (PMID 35732855, 2022). "In this study, for the first time, the relationship of NTN4 with the TME in breast cancer was indicated by bioinformatics." (PMID 35732855, 2022). "Based on data from public databases, NTN4 correlates with breast cancer prognosis and immune infiltration." (PMID 35732855, 2022). "Using UALCAN database, we explored if promoter methylation of NTN4 was related to clinicopathological characteristics of breast cancer patients." (PMID 35732855, 2022). "This study aims to investigate if NTN4 correlates with prognosis and immune infiltration in breast cancer." (PMID 35732855, 2022). "Knockout of NTN4 in breast epithelium increased cell proliferation in vitro and tumor growth in vivo, suggesting that low expression of NTN4 promoted breast cancer development." (PMID 35732855, 2022).
breast carcinoma (continued). "The prognostic landscape of NTN4 and its relationship with immune infiltration in breast cancer were deciphered with public databases and immunohistochemistry (IHC) in tissue samples." (PMID 35732855, 2022). "The expression of nerve guidance factor 4 (NTN4), which is a regulatory molecule of epithelial–mesenchymal transformation in breast adenocarcinoma, was reduced in breast cancer samples." (PMID 36189255, 2022). "Transcription and survival analyses of NTN4 in breast cancer were investigated with cBioPortal database." (PMID 35732855, 2022). "To date, roles for only NTN1 and NTN4 have been described in breast cancer, ovarian cancer, prostate cancer, and pancreatic cancer among endocrine system-related tumors and sex hormone-targeting tumors." (PMID 32251318, 2020). "The NTN4 expression in breast cancer tumors was correlated with longer disease-free survival and overall survival." (PMID 30923634, 2019). "rs60538652, on SIAH2, rs2912774 on FGFR2 and rs67129489 near PGAM1P5/NTN4 were more strongly associated with ER+ or PR+ cases, while rs9383936 near ESR1 was more strongly associated with ER− or PR− breast cancers (Pheterogeneity <0.05)." (PMID 30323354, 2018). "Studies suggests that NTN4 expression is tied to decreases in cell proliferation, as has been observed in corneal and pancreatic epithelium, as well as in a human breast cancer cell line (MCF7)." (PMID 24780490, 2014). "NTN4 is a transmembrane protein whose expression levels positively correlates with better prognosis in breast cancer." (PMID 23758962, 2013). "Several of these genes have been linked to breast cancer (MAPT, HMGCS2, NR2F2, TFAP2B, NTN4, SEC14L2 and LTF)." (PMID 21209903, 2010). "In addition, NTN4 overexpression inhibited breast cancer cells proliferation, migration, invasion and tumour formation, as well as downregulation in N‐cadherin and vimentin expression." (PMID 38546656, 2024). "In addition, the level of netrin-4 in BM is highly correlated with the prognosis of breast cancer, renal cancer, and uveal melanoma." (PMID 37822877, 2023). "Collectively, these data suggest that NTN4 is worthy of further investigation in breast cancer, and it may be a potential biomarker, which can be used to predict the prognosis of breast cancer patients." (PMID 35732855, 2022). "Based on these findings, we aim to explore if NTN4 affects the prognosis of breast cancer patients." (PMID 35732855, 2022). "Promoter methylation of NTN4 exhibited different patterns in breast cancer." (PMID 35732855, 2022). "NTN4 mRNA expression level in breast cancer was explored using UALCAN database." (PMID 35732855, 2022). "The current research has explored NTN4 and its prognostic significance in breast cancer." (PMID 35732855, 2022). "NTN4 is a secreted protein and is downregulated in breast cancer." (PMID 34981672, 2022). "In addition, the frequency of NTN4 gene alteration was low (1.1%), with patterns stratified by molecular subtypes of breast cancer." (PMID 35732855, 2022). "We determined if NTN4 mRNA expression was related to immune infiltration in different cancers by calculating coefficient index of NTN4 mRNA expression with immune infiltration in breast cancer using the TIMER." (PMID 35732855, 2022). "Furthermore, relationship of NTN4 gene alteration with breast cancer patient survival was assessed." (PMID 35732855, 2022). "In addition, this study confirmed that NTN4 may be used as a prognostic marker of breast cancer by analyzing a series of clinical samples from patients with in breast cancer." (PMID 35732855, 2022). "The NTN4 mRNA levels may reflect infiltration of lymphocytes in breast cancer." (PMID 35732855, 2022). "In breast cancer, miR-196a expression correlates with certain HOXC genes involved in tumor progression, while in cervical cancer, it targets netrin 4, influencing cell proliferation and migration." (PMID 39640883, 2024).
breast carcinoma (continued). "In addition, a recent study indicated that NTN4 may support the formation of TME in breast cancer." (PMID 38164180, 2024). "Similarly, few studies have established that NTN4 is significantly upregulated in breast carcinoma effusions compared to patient-matched solid primary and metastatic tumors suggesting that it may be of biological significance along with its prognostic significance." (PMID 37736464, 2023). "Thus, NTN4 promoter methylation may contribute to breast cancer development and progression." (PMID 35732855, 2022). "Finally, in NTN4 interaction gene cluster analysis, signaling pathways were mostly enriched in cell morphogenesis and motility, which may explain the potential involvement of NTN4 in tumor development and progression of breast cancer." (PMID 35732855, 2022). "Overexpression of netrin-4 increases LVD in mouse skin, and breast cancer xenografts overexpressing netrin-4 show enhanced LVD and metastasis." (PMID 22505936, 2012). "In HER2+ breast cancer, NTN4 expression level was not related to tumor purity (r = − 0.097, P = 1.67e−01), whereas only negatively related to CD8+ T cells (r = − 0.352, P = 7.27e−03)." (PMID 35732855, 2022). "Moreover, expression of top five genes (NCEH1, RARRES3, NTN4, CFB and CYP4Z1) that are frequently co-expressed with TNFSF10 in breast cancer patients, have been detected upon transfection with miR-7641 mimic." (PMID 28827731, 2017). "In addition, ROC curve was used to analyze effectiveness of NTN4 mRNA expression level AUC on distinguishing breast cancer tissues from non-tumor tissues." (PMID 35732855, 2022). "Furthermore, no investigation has been focused on the relationship of NTN4 with tumor microenvironment (TME) of breast cancer." (PMID 35732855, 2022).
glioblastoma (12 papers, 2013 to 2024). The most malignant astrocytic tumor (WHO grade IV). "Similar findings were observed in glioblastoma cells, where secreted NTN4 regulates cell proliferation via integrin β4 signaling." (PMID 38164180, 2024). "Among them, high expression of NTN4 attenuates DNA damage-induced senescence in Glioblastoma multiforme (GBM)." (PMID 37352167, 2023). "More importantly, NTN4 protected glioblastoma cells from drug temozolomide-induced senescence, indicating its effect on tumor CS." (PMID 36189255, 2022). "Our previous study showed that Netrin-4 (NTN4) protects glioblastoma cells from TMZ-induced senescence through rescuing the phosphorylation of AKT and ERK." (PMID 30514230, 2018). "In glioblastoma, NTN4 is highly expressed at the tumor invading edge and promotes glioblastoma cell proliferation via ITGB4-Akt signaling." (PMID 30514230, 2018). "In glioblastoma, NTN4 has been proposed to depict a biphasic function: at low physiological ligand concentrations, both proliferation and cell migration increase, whereas at high concentrations, tumor cell growth is inhibited." (PMID 28038459, 2017). "This is consistent with the low expression of NTN4 in glioblastoma cells compared to its expression in healthy tissue." (PMID 28038459, 2017). "Reduced NTN4 expression in glioblastoma cell lines induced by serum starvation significantly decreases proliferation and motility, increasing apoptosis." (PMID 28038459, 2017). "Previous studies have revealed a dose-dependent effect of NTN4 in glioblastoma cell proliferation and motility." (PMID 28038459, 2017). "Previous studies revealed that the effects of Ntn4 on glioblastoma cells are concentration dependent." (PMID 25909166, 2015). "We report here that the suppression of either ITGB4 or NTN4 in glioblastoma cell lines significantly enhances cellular senescence." (PMID 24265816, 2013). "Our recent results reveal that glioblastoma tumors of most patients express low levels of NTN4 and high levels of ITGB4." (PMID 24265816, 2013). "In glioblastoma, high concentrations of NTN4 decrease cell proliferation in cultured glioblastoma cells." (PMID 24265816, 2013). "We find here that suppression of the expression of either ITGB4 or NTN4 in different glioblastoma cell lines leads to cellular senescence, consistently with the results from other ITGB4 silenced cell types." (PMID 24265816, 2013). "In the current work we have explored the effect of NTN4/ITGB4 interaction on TMZ induced glioblastoma cell senescence." (PMID 24265816, 2013). "Current results suggest that NTN4/ITGB4 stimulated AKT activation provides glioblastoma cells with the ability of TMZ resistance." (PMID 24265816, 2013). "In glioblastomas NTN4 is expressed by the tumor cells at the invading edge, and it promotes glioblastoma cell proliferation via integrin beta-4 mediated AKT-mTOR signaling." (PMID 24265816, 2013). "NTN4 promotes the proliferation of glioblastoma cells by activating the AKT-mTOR signaling pathway." (PMID 32251318, 2020). "NTN4 has been implicated in activating multiple oncogenic pathways in gastric cancer, namely Jak/Stat, PI3K/Akt and ERK/MAPK, and it interacts with integrin β4 to promote glioblastoma cell proliferation via the AKT-mTor pathway." (PMID 27172792, 2016). "Based on these data, we conclude that netrin-4 either acts as a pro- or anti-angiogenic factor in vitro, depending on dosage, consistent with netrin-4 regulates glioblastoma cell proliferation and migration in a concentration-dependent manner (0, 50, 200, 3000 ng/mL)." (PMID 25853509, 2015). "Furthermore, NTN4 is expressed at higher levels in the white matter-invading glioblastoma cells than in the tumor cores." (PMID 24265816, 2013). "Therefore, the NTN4/ITGB4 transduced AKT activation possibly influences TMZ triggered glioblastoma cell senescence." (PMID 24265816, 2013). "However, low concentrations of NTN4 promote glioblastoma cell proliferation via integrin beta-4 signaling." (PMID 24265816, 2013).
glioblastoma (continued). "To understand the effects of NTN4 and ITGB4 on glioblastoma cell senescence, we inhibited the expression of these two genes in U251MG cells by using short hairpin RNAs (shRNAs)." (PMID 24265816, 2013). "By Q-RT-PCR, we confirmed that both NTN4 and ITGB4 were expressed in all four analyzed glioblastoma cell lines, namely U251MG, U87MG, U118MG and T98G." (PMID 24265816, 2013). "This suggests that the interaction between NTN4 and ITGB4 can regulate glioblastoma cell senescence." (PMID 24265816, 2013). "We have recently identified the interaction between netrin-4 (NTN4) and integrin beta-4 (ITGB4), which promotes glioblastoma cell proliferation via activating AKT-mTOR signaling pathway." (PMID 24265816, 2013). "We have previously analyzed the expression of NTN4 and ITGB4 genes in the U251MG and U87MG glioblastoma cell lines." (PMID 24265816, 2013). "Consistent with the clinical trials, our bioinformatic analysis of TCGA glioblastoma revealed that neither EGFR nor NTN4 predicts significant survival in TMZ-treated patients." (PMID 30514230, 2018). "Because NTN4/ITGB4 may together activate AKT, we investigated the role of this signaling pathway on the temozolomide resistance of glioblastoma cells." (PMID 24265816, 2013). "To investigate whether the expression levels of MGMT and NTN4/ITGB4 are associated in glioblastoma tissues, we analyzed the expression levels of primary tumors from The Cancer Genome Atlas - Glioblastoma multiforme (TCGA-GBM) repository." (PMID 24265816, 2013). "However, for patients with relatively high expression of NTN4 and ITGB4 in glioblastoma tumors, the prevention of NTN4/ITGB4 interaction or concomitant use of the inhibitors of the AKT pathway may improve the therapeutic benefit of temozolomide." (PMID 24265816, 2013).
cervical cancer (7 papers, 2016 to 2025). A primary or metastatic malignant neoplasm involving the cervix. "Endometrial CSCs are supported by pathways involving TGFβ, BMP2, and Netrin-4/c-Myc signaling, while in cervical cancer, VEGF, IGF-1, Gremlin-1, and TGFβ-mediated circuits enhance stem-like phenotypes and drug resistance." (PMID 41373619, 2025). "miR-196a is overexpressed in serum, Cervical Intraepithelial Neoplasia (CIN) 2-3 and cervical cancer tissues inducing proliferation and migration, diminishing mRNA and protein of Netrin 4 (NTN4) via 3′UTR." (PMID 28216603, 2017). "However, another found that NTN4 was downregulated in cervical cancer tissue, and low expression of NTN4 promoted the capacity of cell proliferation and migration in cervical cancer." (PMID 38546656, 2024). "At a tissue level, NTN4 expression was downregulated in cervical cancer tissues compared to normal controls, implying that NTN4 may play a protective role in cervical cancer pathogenesis." (PMID 37736464, 2023). "LETMD1 (Human Cervical Cancer Oncogene) was detected fused to NTN4 in Sarcoma (SARC)." (PMID 32251318, 2020). "However, other studies examining expression of NTN4 in clinical samples have reported that it is markedly down-regulated in prostate, breast and cervical cancers." (PMID 27172792, 2016).